HYDIN2 (HYDIN axonemal central pair apparatus protein 2 (pseudogene))
Synonyms: formerly HYDINP1
Gene: Transcribed unprocessed pseudogene on chromosome 1 (146,547,367 to 146,898,974, forward strand). Ensembl gene ENSG00000276975.
Diseases named in the same sentence as HYDIN2 in open-access papers:
HYDIN2 is named in the same sentence as 5 diseases in open-access papers, as found by Europe PMC text mining. Sharing a sentence is not in itself a finding about the gene and the disease. The quoted sentences say what the papers report.
microcephaly (2 papers, 2017 to 2022). A congenital or acquired developmental disorder in which the circumference of the head is smaller than normal for the person's age and sex. "It was postulated that HYDIN2 might contribute to the reciprocal macrocephaly/microcephaly phenotype, because mutation of the ancestral HYDIN gene leads to hydrocephalus in mouse." (PMID 28279197, 2017). "We show that the reciprocal macro/microcephaly phenotypes associated with chromosome 1q21 rearrangements can occur without HYDIN2 copy number changes." (PMID 28279197, 2017).
autism (1 paper, 2017). Persistent deficits in social interaction and communication and interaction as well as a markedly restricted repertoire of activity and interest as well as repetitive patterns of behavior. "As an alternative approach, we sought to characterize and compare deleterious coding variation between HYDIN and HYDIN2 among 3484 probands and 2629 healthy controls from families with autism." (PMID 28279197, 2017).
cognitive deficits (1 paper, 2018). "HYDIN2 has been hypothesized to underlie macrocephaly and perhaps cognitive deficits in this syndrome, but assessment of HYDIN2 copy number by microarray is difficult because of extensive segmental duplications." (PMID 30155272, 2018).
Hydrocephalus (1 paper, 2017). Hydrocephalus is an active distension of the ventricular system of the brain resulting from inadequate passage of CSF from its point of production within the cerebral ventricles to its point of absorption into the systemic circulation. "Loss or gain of HYDIN2 has been hypothesized to underlie these head circumference phenotypes in light of its expression in brain, its inclusion in the typical rearrangement interval, and the association of homozygous losses of HYDIN in mouse with hydrocephalus." (PMID 28279197, 2017).
HYDIN2 also shares sentences with these, for which no sentence is quoted: Macrocephaly (1 paper).